CLTB (clathrin light chain B)
Description:
Clathrin is the major protein of the polyhedral coat of coated pits and vesicles.
Synonyms: Lcb
Tractability: Antibody: its Gene Ontology location is reachable by antibodies, with high confidence; UniProt places it where antibodies can reach, with medium confidence; the Human Protein Atlas places it where antibodies can reach. PROTAC: ubiquitination databases record sites on it; its protein half-life has been measured.
Target class: Structural protein
Gene: Protein-coding gene on chromosome 5 (176,392,494 to 176,416,557, reverse strand). Ensembl gene ENSG00000175416.
Subcellular location: Cytoplasmic vesicle membrane; Membrane, coated pit
Subcellular location (Human Protein Atlas): Vesicles; Cytosol; Plasma membrane
Pathways (Reactome):
Vesicle-mediated transport: Cargo recognition for clathrin-mediated endocytosis; Clathrin-mediated endocytosis; Formation of annular gap junctions; Gap junction degradation; Lysosome Vesicle Biogenesis
Signal Transduction: WNT5A-dependent internalization of FZD2, FZD5 and ROR2; WNT5A-dependent internalization of FZD4
Developmental Biology: EPH-ephrin mediated repulsion of cells
Gene Ontology:
Molecular function: protein binding; clathrin heavy chain binding; peptide binding; structural molecule activity
Biological process: chromosome segregation; clathrin coat disassembly; clathrin-dependent endocytosis; intracellular protein transport; mitotic cell cycle; mitotic spindle organization; synaptic vesicle endocytosis; vesicle-mediated transport
Cellular component: plasma membrane; clathrin coat; clathrin vesicle coat; clathrin-coated endocytic vesicle; cytosol; kinetochore microtubule; mitotic spindle microtubule; synaptic vesicle membrane; ciliary membrane; clathrin coat of coated pit; clathrin coat of trans-Golgi network vesicle; cytoplasmic vesicle membrane; membrane; presynaptic endocytic zone membrane; trans-Golgi network
Genetic constraint (gnomAD): Loss-of-function variants: 10 observed, 29.92 expected, observed/expected ratio (o/e) 0.33, 90% interval 0.2 to 0.57. The upper end of that interval is the gene's LOEUF score, 0.57, which puts it in group 2 of 6, group 1 being the genes least tolerant of losing a copy. Missense variants: 260 observed, 306.78 expected, observed/expected ratio (o/e) 0.85, 90% interval 0.76 to 0.94. Synonymous variants: 102 observed, 122.92 expected, observed/expected ratio (o/e) 0.83, 90% interval 0.71 to 0.98.
Homologues: Orthologues: chimpanzee CLTB (100% identical), macaque CLTB (99% identical), dog CLTB (98% identical), pig CLTB (97% identical), guinea pig CLTB (96% identical), mouse Cltb (84% identical), rat Cltb (84% identical), rabbit CLTB (83% identical), tropical clawed frog cltb (71% identical), zebrafish cltb (63% identical), Drosophila melanogaster Clc (34% identical), Caenorhabditis elegans clic-1 (25% identical). Paralogues in human: CLTA (56% identical).
Diseases named in the same sentence as CLTB in open-access papers:
CLTB is named in the same sentence as 17 diseases in open-access papers, as found by Europe PMC text mining. Sharing a sentence is not in itself a finding about the gene and the disease. The quoted sentences say what the papers report.
glioma (2 papers, 2008 to 2023). A benign or malignant brain and spinal cord tumor that arises from glial cells (astrocytes, oligodendrocytes, ependymal cells). "These genes had varying degrees of glioma-specific splicing and included APPA4, CLTB, DYNC1I2, NF1, RTN4 and TNC." (PMID 18474104, 2008).
Huntington disease (2 papers, 2009 to 2021). Huntington disease (HD) is a rare neurodegenerative disorder of the central nervous system characterized by unwanted choreatic movements, behavioral and psychiatric disturbances and dementia. "These include genes in the pathways for amyotrophic lateral sclerosis (NEF3, NEFL, NEFH), Huntington's disease (CALM3, CLTC, CLTB), neurodegenerative disorders (APLP1, NEFH, FBXW7), Parkinson's disease (GPR37) and prion disease (APLP1, NFE2L2)." (PMID 19948073, 2009).
hepatocellular carcinoma (1 paper, 2025). A malignant tumor that arises from hepatocytes. "This study aims to elucidate the role of CLTB in the pathogenesis of hepatocellular carcinoma (HCC) and its clinical implications." (PMID 40820941, 2025).
cancer (4 papers, 2022 to 2025). A tumor composed of atypical neoplastic, often pleomorphic cells that invade other tissues. "In the pan‐cancer analysis of The Cancer Genome Atlas (TCGA) database, CLTB showed upregulated expression in various malignant tumors, with HCC being one of the most significantly upregulated tumors." (PMID 40820941, 2025). "Upregulation of clathrin light chain b has been shown to couple with dynamin-1 in cancer cells, which leads to adaptive clathrin-mediated endocytosis and increases metastasis." (PMID 37920509, 2023). "Currently, there is limited mechanism investigation of clathrin light chain B (CLTB) in cancer." (PMID 38214842, 2024).
tumor (2 papers, 2022 to 2025). "Subsequent analysis combining TCGA and Gene Expression Omnibus (GEO) databases demonstrated significantly elevated CLTB expression in HCC tumor tissues compared to normal liver tissues." (PMID 40820941, 2025). "Given that clathrin‐mediated endocytosis is the key mechanism for sEV uptake, this study further investigated the functional implications of CLTB‐enriched sEVs in tumor vascular remodeling." (PMID 40820941, 2025). "Immunohistochemical analysis showed significant differences in CLTB expression in normal and tumor tissues, with 75% (45/60) of tumor tissues showing intense positive staining for CLTB, which was markedly elevated compared to paracancerous tissues." (PMID 40820941, 2025). "CLTB overexpression correlates with poor prognosis, while preclinical models reveal that targeting CLTB or SH3KBP1 synergizes with sorafenib to suppress tumor growth and angiogenesis." (PMID 40820941, 2025). "In addition, in 58.3% (35/60) of cases, the expression level of CLTB was significantly higher in tumor tissues than in matched paracancerous tissues." (PMID 40820941, 2025). "Targeting CLTB or SH3KBP1 synergizes with sorafenib to suppress tumor growth in vivo." (PMID 40820941, 2025). "Furthermore, clinical cohort analysis indicated significantly increased PCLAF immunoreactivity in tumor tissues relative to normal liver tissues, and the PCLAF expression pattern was congruent across patients exhibiting high PCLAF and CLTB expressions." (PMID 40820941, 2025). "Mechanistically, CLTB regulated HCC development by activating the NF‐κB–PCLAF axis and stabilized its protein expression through an interaction with SH3KBP1, thereby remodeling the tumor microenvironment." (PMID 40820941, 2025).
CLTB also shares sentences with these, for which no sentence is quoted: amyotrophic lateral sclerosis (1 paper); Cirrhosis (1); inflammatory bowel disease (1); lymphoma (1); nasopharyngeal carcinoma (1); pancreatic cancer (1); Parkinson disease (1); prion disease (1); Salmonella Infections (1); triple-negative breast carcinoma (1); viral hepatitis (1); viral infection (1).